DUSP1 (dual specificity phosphatase 1)
Diseases named in the same sentence as DUSP1 in open-access papers (continued):
Sharing a sentence is not in itself a finding about the gene and the disease.
Obesity (28 papers, 2010 to 2025). Accumulation of substantial excess body fat. "Obesity and hyperlipidemia in the setting of adverse social determinants negatively impact NK cells via a pathway involving DUSP1/mTOR/TFEB, contributing to increased heart disease risk." (PMID 39718832, 2024). "Our study advances the field by establishing Dusp1 as a central modulator of obesity and LDL-mediated NK dysfunction in at-risk individuals chronically exposed to aSDoH." (PMID 39718832, 2024). "DUSP1 single nucleotide polymorphisms are also associated with obesity-related metabolic complications." (PMID 39718832, 2024). "While DUSP1−/− mice were resistant to HFD-induced obesity MKP-1-LKO mice were more susceptible, but were still protected against hepatic steatosis." (PMID 30401534, 2019). "An extensive molecular analysis of the human DUSP1 gene was undertaken to test for associations between DUSP1 polymorphisms and obesity-related metabolic complications in a cohort of severely obese patients undergoing a bariatric surgery." (PMID 23986905, 2013). "With obesity being characterized by low-grade inflammation, the impact of phenotype-associated SNPs identified here may be exerted through a modulation of DUSP1 antioxidative and anti-inflammatory functions." (PMID 23986905, 2013). "Additionally, community-informed interventions targeting aSDoH, obesity, and hyperlipidemia might impact Dusp1-driven NK cell dysfunction to reduce CVD or cancer risk by promoting physical activity and other lifestyle changes." (PMID 39718832, 2024). "In addition, the m6A methylation levels of genes related to these diseases also changed after DBS; such changes occurred with Slc1a6 (an OCD-associated gene: hypermethylation), Kcnj11 (an obesity-associated gene: hypermethylation), and Dusp1 (an addiction-associated gene: hypermethylation)." (PMID 33343932, 2020). "Future studies should further examine the expression of Dusp1 in an immune subset–specific manner and will need to clarify the role of chronic environmental and psychosocial stressors in obesity-related NK modulation." (PMID 39718832, 2024). "Unbiased omics-based analyses identified DUSP1 as a crucial and common regulator of obesity- and LDL-mediated NK cell dysfunction." (PMID 39718832, 2024). "In our study, DUSP1 levels were found to be associated with CVD despite statin treatment and diabetes status (p < 0.05), whereas hsCRP mainly correlated with obesity markers." (PMID 30647800, 2018). "In the control group, there was a statistically significant positive correlation between DUSP1 levels and all obesity indicators and SBP." (PMID 30647800, 2018). "While the weight of the male DUSP1 control animals was on average higher than the KO group, we did not observe any differences in OA development which is known to be influenced by obesity in humans." (PMID 26562438, 2015). "Results presented here demonstrate an impact of DUSP1 gene variations on obesity-related complications." (PMID 23986905, 2013). "Our data demonstrate a pathway by which obesity and hyperlipidemia in the setting of aSDoH may relate to NK cell dysfunction, making DUSP1 an important target for further investigation of health disparities." (PMID 39718832, 2024). "Although Dusp1 has not previously been implicated in obesity- or LDL-related immune suppression, it is strongly linked to prevalent obesity." (PMID 39718832, 2024). "Moreover, our transcriptomic analysis identifies DUSP1 as a common factor linking obesity- and LDL-mediated regulation of NK cells." (PMID 39718832, 2024). "This obesity-induced Dusp1 upregulation is reduced by physical activity." (PMID 39718832, 2024). "In summary, our data implicate Dusp1 as a crucial obesity- and hyperlipidemia-induced factor that may promote CVD and cancer risk through its immunosuppressive effects." (PMID 39718832, 2024). "Identification of DUSP1 involvement in NK cell dysfunction related to obesity and LDL." (PMID 39718832, 2024).
Obesity (continued). "Our finding that LDL and obesity highly induced DUSP1 in NK cells led us to hypothesize that Dusp1 might mediate lipid/obesity-induced NK cell functional changes." (PMID 39718832, 2024). "Interestingly, IL-6 receptor levels have been reported to reflect OSA severity; FOS, FOSB, and JUN have been demonstrated to be involved in obesity, osteoporosis, and colorectal cancer; and DUSP1 is upregulated in CIH in OSA patients." (PMID 36468038, 2022). "Therefore, our data suggest that Dusp1 may provide a novel mechanistic link between obesity, LDL, and NK cell dysfunction." (PMID 39718832, 2024). "Furthermore, diet-induced obesity has an inflammatory component and the role(s) of DUSP1/MKP-1 in regulating immune responses may also be a confounding factor." (PMID 30401534, 2019). "The first indication that DUSP1/MKP-1 might play a role in regulating metabolic homeostasis came with the finding that DUSP1−/− mice were resistant to diet-induced obesity and that this reflected a higher level of energy expenditure, but not overall activity in the null mice." (PMID 30401534, 2019). "One of our central findings is that obesity, as well as LDL, reduced NK cytotoxicity and function through Dusp1." (PMID 39718832, 2024). "The current study reports underexpression of DUSP1 in VAT of severely obese individuals with the MetS, thus extending the potential pathophysiological importance of this gene to obesity-related metabolic disease." (PMID 23986905, 2013). "Together, these results strongly suggest that, for individuals exposed to aSDoH, obesity and hyperlipidemia promote NK cell dysfunction at least partially through pathways initiated by LDL involving Dusp1-mediated regulation of mTOR- and TFEB-facilitated lysosomal biogenesis." (PMID 39718832, 2024). "DUSP1-deficient mice by contrast do not have improved glucose tolerance, despite being protected from HFD-induced obesity." (PMID 25375135, 2014). "Studies reporting roles for the MAPK dual specificity phosphatases DUSP1 and DUSP9 during inflammation, obesity and insulin sensitivity, prompted us to investigate what function DUSP2 might play in these processes." (PMID 25375135, 2014). "Our analysis of differentially expressed genes in VAT of severely obese individuals with and without MetS revealed a potential implication of the DUSP1 gene in the interindividual variability observed in obesity-related metabolic complications." (PMID 23986905, 2013). "Functional redundancy amongst the nuclear specific DUSPs, which in addition to DUSP2 include DUSP1, DUSP4 and DUSP5, may also be a contributing factor in DUSP2 not playing a unique role in obesity-associated WAT inflammation." (PMID 25375135, 2014). "Additionally, we could not determine if Dusp1 might indeed be regulated by the exposure to chronic stress as an aSDoH and if this precedes obesity development." (PMID 39718832, 2024).
ovarian carcinoma (28 papers, 2010 to 2025). A malignant neoplasm originating from the surface ovarian epithelium. "SGK1 and another top upregulated DEG, DUSP1, have both been implicated in chemoresistance and apoptosis inhibition in ovarian cancer, with our own research showing that a dual inhibitor of DUSP1 and DUSP6 reversed chemoresistance in ovarian cancer cells." (PMID 36131935, 2022). "At this time, ClinicalTrials.gov only demonstrates a single study in ovarian cancer in which DUSP1 expression is being assessed." (PMID 41158869, 2025). "The high variation in DUSP1 expression was observed in colon, prostate, liver, epithelial and advanced epithelial ovarian cancer, and bladder cancers." (PMID 41158869, 2025). "In a study focusing on the resistance of human ovarian cancer cells, researchers examined the role of dual-specificity phosphatase 1 (DUSP1) in the development of resistance to paclitaxel in these cells." (PMID 39852139, 2025). "They found that the overexpression of DUSP1 upregulated P-glycoprotein expression, which facilitated the efflux of anticancer drugs, thereby leading to resistance in human ovarian cancer cells." (PMID 39852139, 2025). "Several studies demonstrated that DUSP1 affects ovarian cancer (OC) progression by targeting MAPK activities, AMPK, and mTORC pathways." (PMID 41158869, 2025). "Chronic adrenergic (norepinephrine) stimulation increases DUSP1 expression, which impairs paclitaxel and cisplatin chemotherapy in vitro and in vivo in ovarian cancer." (PMID 41158869, 2025). "Further, DUSP1 reduced chemotherapy efficacy; for example, dexamethasone (a synthetic glucocorticoid) is used to inhibit the side effects of chemotherapy in ovarian cancer patients induced DUSP1 expression and reduced chemotherapy impact." (PMID 41158869, 2025). "CSGALNACT2 suppresses ovarian cancer migration and invasion via DUSP1 modulation of the MAPK/ERK pathway through RNA-seq, KEGG analysis, and Western blotting." (PMID 38082211, 2024). "In prior studies, Dusp1 has been shown to impact mTOR in ovarian cancer, and TFEB, in turn, has been shown to negatively bind and regulate the DUSP1 promotor in melanoma." (PMID 39718832, 2024). "Previous studies focused on the potential use of DUSP1, DUSP4, and DUSP6 as diagnostic markers in ovarian cancer." (PMID 37476896, 2023). "Norepinephrine treatment of ovarian cancer cells increases expression of DUSP1, a phosphatase related to preventing apoptosis in cancer cell lines." (PMID 37326414, 2023). "Researchers also found that the expression of DUSP1 is downregulated in ovarian cancer stem cells and that DUSP1 is regarded as a prognostic seed gene in OVCA." (PMID 35911442, 2022). "In a xenograft model of ovarian cancer, stimulation of the adrenergic response by restraint stress significantly increased tumour burden and the expression of DUSP1." (PMID 35582576, 2019). "Knockdown of DUSP1 expression in a subsequent ovarian cancer xenograft model significantly restored the efficacy of chemotherapy - indicating that the DUSP1 expression induced by adrenergic activation has a functional role in the protection from apoptosis." (PMID 35582576, 2019). "Induced reexpression of DUSP1 in ovarian cancer cell lines decreases their anchorage-dependent and -independent growth, indicating a potential role of this phosphatase in ovarian cancer progression." (PMID 25201346, 2014). "We have also previously shown that DUSP1 is differentially expressed in epithelial ovarian cancer as compared with normal ovarian epithelium." (PMID 25201346, 2014). "In addition, the overexpression of DUSP1 is correlated with poor patient survival in ovarian cancer." (PMID 40361912, 2025). "Mechanistically, catecholamines induced the expression of DUSP1, a MAPK phosphatase linked to the promotion of chemoresistance, through direct action of the β-2 adrenergic receptor on the promoter, which in turn protects ovarian cancer cells from apoptosis." (PMID 35582576, 2019).
ovarian carcinoma (continued). "Also realizing the role of DUSP1 in regulating autophagy suggests that suppression of DUSP1 may enhance the therapeutic activity of rapamycin in ovarian cancer." (PMID 37476896, 2023). "Based on whole-genome cDNA microarray analysis, KRASG12D/K104Q decreased expression of NPIPA2, DUSP1 and IL6 in lung and ovarian cancer cells." (PMID 33060649, 2020). "In ovarian carcinoma, in vitro assays showed that in glucocorticoid receptor (GR)-positive HeyA8 and SKOV3 cells, dexamethasone (100 nM) treatment upregulated the pro-survival genes SGK1, and MKP1/DUSP1 and inhibited carboplatin/gemcitabine-induced cell death." (PMID 33542904, 2020).
prostate carcinoma (25 papers, 2000 to 2026). A carcinoma that arises from epithelial cells of the prostate gland. "Our study provides new insights about the molecular mechanisms underlying the effects of the phosphatase DUSP1 on metastasis-associated events in prostate cancer." (PMID 33800291, 2021). "The role of dual specificity phosphatase 1 (DUSP1) in metastasis-associated processes in prostate cancer and its impact on patient outcome remains to be elucidated." (PMID 33800291, 2021). "DUSP1 has been shown to be upregulated in early phases of epithelial carcinogenesis in bladder, colon, and prostate cancers with progressive loss on expression with higher histological grades and in metastasis." (PMID 21547253, 2011). "Based on all these data, we conclude that the ratio between the expression levels of DUSP1 and Snail could be an important biomarker for diagnostic purposes in prostate cancer, as they may serve for identifying patients at risk for an unfavorable clinical outcome." (PMID 33800291, 2021). "Activation of DUSP1 by chemopreventive drugs at late stages of prostate cancer (PCa) will be a promising strategy for controlling PCa." (PMID 41158869, 2025). "In prostate cancer, DUSP1 is known to dephosphorylate the JNK signaling pathway, suppressing tumor cell migration, invasion, and angiogenesis." (PMID 40535772, 2025). "Conversely, in hepatocellular carcinoma, prostate cancer, and head/neck squamous cell carcinoma, DUSP1 exhibits significant downregulation as a tumor suppressor." (PMID 40535772, 2025). "It is worth noting that studies have shown that CEP can inhibit the ERK signaling pathway by enhancing the expression of DUSP1, thereby exerting anti-tumor effects on prostate cancer in vitro and in vivo." (PMID 41368570, 2025). "In hepatocellular carcinoma 5, prostate cancer 6, head and neck squamous cell carcinoma 7 as well as other tumor types, DUSP1 was significantly down-regulated in aggressive phenotypes." (PMID 37057290, 2023). "DUSP1 is highly expressed in a range of tumors, including lung, breast, ovarian, gastric, and prostate cancers, while low expression in HCC." (PMID 37503331, 2023). "This study demonstrates that HXL131 exhibited excellent anti-prostate cancer activity and inhibited the growth and metastasis of prostate cancer cells by regulating the expression of DUSP1 and TNFSF9." (PMID 36142828, 2022). "ATF3 expression was related to glycosaminoglycan degradation, pathways in cancer, prostate cancer, and TGF-β signaling, and DUSP1 was associated with adipocytokine signaling, graft vs. host disease, pathways in cancer, and small cell lung cancer." (PMID 35372438, 2022). "For instance, DUSP1 overexpression favors the growth of prostate cancer, driving tumor progression, whereas it facilitates the apoptosis of neuroblastoma cells and therefore has a detrimental effect on tumor cell survival." (PMID 36589747, 2022). "All these results indicate that DUSP1 downregulates Snail expression, which in turn results in a further decrease in migration and invasion of prostate cancer cells." (PMID 33800291, 2021). "Consistently, DUSP1 overexpression in androgen-independent prostate cancer cells promotes apoptosis through inhibition of the p38 mitogen-activated protein kinase (p38MAPK)/nuclear factor-kappaB (NF-kB) signaling pathway." (PMID 33800291, 2021). "To study the role of DUSP1 in the migration and invasion of prostate cancer cells, we first analyzed the effect of DUSP1 knockdown on Snail expression in DU145 cells." (PMID 33800291, 2021). "Dual specificity phosphatase 1 (DUSP1) is crucial in prostate cancer (PC), since its expression is downregulated in advanced carcinomas." (PMID 33800291, 2021). "In agreement with this, here, we demonstrate that DUSP1 downregulates Snail expression and inhibits migration and invasion in prostate cancer cells." (PMID 33800291, 2021).
prostate carcinoma (continued). "Since our data in prostate cancer cells revealed that DUSP1 inhibits JNK and ERK and these MAPKs negatively regulated Snail expression, we also analyzed the levels of activated JNK and ERK (pJNK and pERK) in patient samples." (PMID 33800291, 2021). "Parallel with the prostate cancer, a similar function of DUSP1 was found in pancreatic cancer, as immunohistochemistry revealed an 8.1‐fold increase in mean DUSP1 mRNA level in pancreatic cancer tissues compared with normal pancreatic tissues." (PMID 27227569, 2016). "Downregulation of DUSP1 with concomitant promoter hypermethylation and loss of heterozygosity at the DUSP1 locus was reported in HCC, and epigenetic regulation of DUSP1 expression was suggested in prostate cancer." (PMID 23986905, 2013). "DUSP1 expression has been previously related to different stages of human prostate carcinomas." (PMID 33800291, 2021). "Interestingly, we also demonstrate in this work the existence of an inverse correlation between DUSP1 and Snail expression levels in patients with different stages of prostate cancer." (PMID 33800291, 2021). "Overall, all these data suggest that the role that DUSP1 plays as a tumor suppressor in prostate cancer is complex and depends on the specific inactivation of one or the other MAPK, which ultimately controls either cell apoptosis, or cell migration and invasion." (PMID 33800291, 2021). "Our results reveal that this phosphatase reduces Snail expression and impairs cell migration and invasion in prostate cancer cells through a mechanism involving the inhibition of DUSP1 molecular targets, c-Jun N-terminal kinase (JNK) and extracellular-signal-regulated kinase (ERK)." (PMID 33800291, 2021). "Furthermore, DUSP1 overexpression in androgen-independent prostate cancer cells induces apoptosis through both p38MAPK and NF-kB dependent mechanisms." (PMID 33800291, 2021). "Moreover, we addressed the correlation of DUSP1 expression with Snail and activated MAPKs levels in samples from patients diagnosed with benign hyperplasia or prostate carcinoma, studying its implication in tumor prognosis and survival." (PMID 33800291, 2021). "Moreover, DUSP1 is also involved in the pro-apoptotic effects of the chemopreventive molecule resveratrol in prostate cancer cells." (PMID 33800291, 2021). "High expression of DUSP1 induces apoptosis in prostate cancer cells." (PMID 29383165, 2017). "DUSP1 expression was found to be upregulated in prostatic cancer compared with normal tissues." (PMID 27227569, 2016). "USP33 could inhibit docetaxel-induced apoptosis of prostate cancer cells, including androgen-independent prostate cancer cells, mechanistically, USP33 could inhibit the Lys48 (K48)-linked polyubiquitination of DUSP1 which led to impaired JNK activation and apoptosis in prostate cancer." (PMID 37322017, 2023). "However, despite all these studies showing DUSP1 as an apoptosis inducer in prostate cancer, the role of this phosphatase in cell migration and invasion in these kind of tumors remains largely unknown." (PMID 33800291, 2021). "Finally, and more interestingly, we evidence that the levels of all proteins tested are related to clinical outcome, suggesting that the ratio between the expression of DUSP1, Snail, and activated JNK and ERK is an important marker for diagnostic purposes in prostate cancer." (PMID 33800291, 2021). "Therefore, in this work, we aimed to investigate whether DUSP1 is involved in the motility of prostate cancer cells and whether this protein regulates the signaling pathways that control these processes." (PMID 33800291, 2021).